ABCB1 (ATP binding cassette subfamily B member 1)
Diseases named in the same sentence as ABCB1 in open-access papers (continued):
Sharing a sentence is not in itself a finding about the gene and the disease.
cancer (continued). "While certain drugs have been designed to inhibit ABCB1 activity, aiming to enhance the effectiveness of cancer therapies, such as the calcium channel blocker verapamil, a major concern arises from the expression of these transporters also in normal cells, which may result in unacceptable toxicity." (PMID 39272999, 2024). "Therefore, high expression of ABCB1 typically leads to chemotherapy resistance, as it could extrude drugs to prevent them from reaching therapeutic concentrations in cancer cells." (PMID 39229920, 2024). "Pgp (P-glycoprotein or ABCB1) is present in normal tissues, such as the liver, kidney, gastrointestinal tract, and blood–brain barrier; therefore, reversing multidrug resistance via blockade of Pgp holds a great challenge; therefore, cancer-selective approaches are principally expected." (PMID 39065573, 2024). "In addition, overexpression of ABCB1 is not limited to specific cancer types, and ABCB1 inhibitors could therefore contribute to the treatment of a broad range of cancers." (PMID 39003409, 2024). "Overexpression of ABCB1 in cancer cells could potentially result in multi-drug resistance tumours." (PMID 36707434, 2023). "In addition, studies have shown that some natural compounds, such as menthol, combine with non-toxic digitalis glycosides to enhance cytotoxicity and inhibit cancer cells proliferation by downregulating the expression of ATP binding cassette subfamily B member 1 (ABCB1)." (PMID 37007039, 2023). "However, three of these transporters are expressed in cancer cells and specifically have been associated with MDR: P-glycoprotein (P-gp or ABCB1), multidrug resistance-associated protein 1 (MRP1 or ABCC1), and the breast cancer resistance protein (BCRP or ABCG2)." (PMID 36678870, 2023). "Therefore, inhibition of ABCB1 expression or activity could increase the accumulation of anticancer drugs within the cancer cells, enhancing their cytotoxicity and restoring their efficacy." (PMID 36674503, 2023). "Thus, discovering ABCB1 inhibitors can reverse the MDR in cancer cells." (PMID 37513931, 2023). "Some preclinical studies have suggested that CDK4/6i, namely palbociclib, can be a substrate for the ABCB1 and/or ABCG2 transporters, which could inclusively affect their ability to cross the blood–brain barrier and decrease anticancer efficacy in cancer cells overexpressing the ABCB1." (PMID 37835528, 2023). "Therefore, determining whether existing anticancer drugs are ABCB1 substrates could predict the treatment outcome to develop improved cancer therapy regimens via combination." (PMID 35281897, 2022). "The wide use of chemotherapeutic drugs that are substrates of ABCB1 including paclitaxel and doxorubicin could lead to the activation/overexpression of ABCB1, at the same time, the overexpression of ABCB1 confers resistance to these drugs in cancer cells and cancer patients." (PMID 35281897, 2022). "Furthermore, another study showed chemotherapeutic agents stimulated the secretion of ABCB1-enriched exosomes from drug-resistant cells and increased the transfer of ABCB1 to the recipient cancer cells, thus assisting these sensitive cancer cells in developing the resistant phenotype." (PMID 36176765, 2022). "P-glycoprotein (P-gp; ABCB1) is the most well-characterized ATP-binding cassette (ABC) multidrug efflux transporter known to actively transport a wide variety of cytotoxic and molecularly targeted drugs out of cancer cells, causing multidrug resistance (MDR) and poor prognosis in cancer patients." (PMID 35565470, 2022). "Native CDK6 may have a role in maintaining ABCB1-mediated MDR of cancers." (PMID 35459184, 2022). "In this study, we examined whether infigratinib (BGJ 398), a potent and selective FGFR1-4 inhibitor can reverse the resistance of ABCB1-overexpressing cancer cells to the conventional chemotherapeutic agents PTX and doxorubicin (Dox), a topoisomerase II inhibitor." (PMID 35327403, 2022).
cancer (continued). "Altogether it seems that the status of the ABCB1 polymorphism may be one of the numerous factors that affect the metabolism of cancer (development and therapy response) but without a leading role in this phenomenon." (PMID 35627114, 2022). "Differing from bulk cancer cells, this liver cancer stem cell subpopulation displays resistance to traditional chemotherapeutic drugs via overexpression of the ATP-binding cassette transporters (i.e., ABCB1, ABCG2, and ABCC1), which serve as pumps to actively expel small molecular drugs." (PMID 36358973, 2022). "Also, as an ATP-binding cassette member, ABCB1 known as P-glycoprotein (P-gp) has been identified as one of the important mechanisms of drug resistance through boosting the efflux of chemotherapeutic drugs from cancer cells." (PMID 33981772, 2021). "One such mechanism may relate to the ability of resistant cells to evade drug-induced cell death due to activation of anti-apoptotic mechanisms; co-deregulation of ABCB1 and apoptotic proteins was previously shown to correlate with a multifactorial resistant phenotype in cancer cells." (PMID 33799432, 2021). "Consequently, ABCB1 and ABCG2 are often associated with the development of multidrug resistance (MDR) in human cancer cells that could result in relapse and treatment failure in cancer patients." (PMID 33807514, 2021). "However, CSCs and hypoxia-adapted cancer cells may be less susceptible to small-molecule radiosensitizers due to the overexpression and high activity of membrane transporters ABCG2, ABCB1 and others that pump drugs out of the target cell." (PMID 33806538, 2021). "Thus, the modulation of ABCB1 activity has been explored as a strategy for cancer treatment." (PMID 34299488, 2021). "Therefore, instead of synthesizing novel modulators, an alternative approach is to explore the possibility of repurposing FDA-approved tyrosine kinase inhibitors (TKIs) to resensitize ABCB1- or ABCG2-overexpressing multidrug-resistant cancer cells to chemotherapeutic agents." (PMID 32466597, 2020). "Interestingly, in cancer patients without therapy, ABCB1 mutations indeed has a significant impact on reducing cancer survival rates, likely reflecting gain-of-function mutations of ABCB1 in these groups." (PMID 34541464, 2020). "Among the ABC proteins, three transporters, P-glycoprotein (P-gp or ABCB1), the multidrug-resistance-associated protein-1 (MRP1 or ABCC1) and the breast cancer resistance protein (BCRP or ABCG2) are mainly associated with cancer MDR being overexpressed in many cell lines." (PMID 32290281, 2020). "In addition, both binding interactions between RN486 and human ABCB1 protein worked in blocking the efflux of anti-cancer drugs from ABCB1, which leading to the increased intracellular concentration of chemotherapeutic drugs like paclitaxel and rendering RN486 of potential reversal effect." (PMID 32984343, 2020). "Indeed, the ABCG2 and ABCB1 transporters play a major role in MDR-related cancers." (PMID 33158067, 2020). "The lack of ABCB1 mRNA mutations without significantly altering ABCB1 upstream transcription prompted us to extend our initial aim to better understand the intractability of ABCB1 exons to drug-induced or drug-selected mutations in our cancer models." (PMID 34541464, 2020). "Furthermore, we found that the drug transport mediated by ABCB1 and ABCG2 was inhibited by sitravatinib in a concentration-dependent manner but the protein expression of ABCB1 and ABCG2 was not significantly altered by sitravatinib in multidrug-resistant cancer cells overexpressing ABCB1 or ABCG2." (PMID 31941029, 2020). "Furthermore, numerous in vitro and in vivo studies indicate that the inhibition of the efflux function and/or expression of the ABCB1 or ABCG2 transporter can significantly increase the efficacy of certain anticancer drugs in various types of cancers that overexpress these ABC transporters." (PMID 33158067, 2020).
cancer (continued). "Overcoming the multi-drug resistant phenotype by targeting ABCB1 in cancer cells at the functional or transcriptional level is a constant topic of anti-cancer research, which will allow to re-use anthracyclines, like doxorubicin, as highly effective anti-cancer drugs in CRC." (PMID 32391276, 2020). "However, under the “no therapy” condition, the overall cancer survival rate in cancer patients with mutated ABCB1 (n = 711) was indeed significantly decreased when compared with unmutated ABCB1 control (n = 6,278) (log-rank test, P-value = 7.93E-3)." (PMID 34541464, 2020). "Therefore, ABCB1 may positively influence cancer patient survival by exporting these and other unknown endogenous substrates that may fuel or stimulate cancer growth." (PMID 33202946, 2020). "None of the main drugs received by PAAD or SKCM patients were ABCB1 substrates; therefore, the association of ABCB1 with favourable OS could not be attributed to drug efflux in these two cancers." (PMID 33202946, 2020). "Cancer stem cells (CSCs) were identified as a “side population” (SP) by flow cytometric analyses based on the efflux of Hoechst dye by the family of adenosine triphosphate (ATP)-binding cassette (ABC) drug transporters such as ABCB1 and ABCG2 present at the plasma membrane." (PMID 31867270, 2019). "Chemotherapeutic agents stimulate the secretion and recycling of ABCB1-enriched EVs through the dysregulation of Rab8B and Rab5, leading to a significant increase of ABCB1 intercellular transfer, thus assisting sensitive cancer cells to develop an urgent resistant phenotype." (PMID 31830995, 2019). "Together, these results suggest that high ABCB1 expression and enhanced drug efflux capacity are uniquely conserved in multiple bat species and may contribute to reducing DNA damage and perhaps, in turn, cancer incidence in bats." (PMID 31249297, 2019). "In order to study whether or not the classical MDR mechanisms impede the cytotoxic activity of BetA toward cancer cells, we investigated multidrug-resistant P-glycoprotein (MDR1/ABCB1)-overexpressing CEM/ADR5000 cells and drug-sensitive parental CCRF-CEM cells using a resazurin assay." (PMID 29867487, 2018). "Nonetheless, it has been reported that clinical resistance to chemotherapy in a series of cancers is strongly associated with the overexpression of the ABC transporters, and overexpression of ABCB1 and ABCG2 in cancers may come with poor prognosis and high risk of death." (PMID 30425643, 2018). "Therefore, we performed in vitro experiments to evaluate if olmutinib could reverse MDR in cancer cells overexpressing ABCB1, ABCG2, or ABCC1 transporters." (PMID 30356705, 2018). "Therefore, we performed in vitro experiments to observe whether olmutinib could reverse MDR in cancer cells overexpressing ABCB1, ABCG2, or ABCC1 transporters." (PMID 30356705, 2018). "Therefore, 15k may have the potential to inhibit MDR in certain cancer cells mediated by the overexpression of ABCB1 and/or ABCG2 transporters." (PMID 28824426, 2017). "The historically first identified mammalian ABC drug transporter was P-glycoprotein (P-gp), encoded by multidrug resistance gene 1 (MDR1/ABCB1) and conferring multidrug resistance by expelling a wide range of structurally unrelated anticancer drugs out of cancer cells." (PMID 28375174, 2017). "Thus, HSP90-dependent cancer cells that have restored HSP90 function in the presence of PU-H71 via an HSP90α Y142N mutation or amplification and overexpression of ABCB1 may be targeted by alternative HSP90 inhibitors, such as ganetespib." (PMID 28032595, 2017). "Therefore, ABCB1 inhibitors may be candidates for combination therapy with SNS-032 that increase SNS-032 efficacy through (re)sensitization of ABCB1-expressing cancer cells, possibly reducing resistance formation." (PMID 27517323, 2016). "However, ABCB1 inhibitors failed in a number of clinical cancer trials." (PMID 26887049, 2016).
cancer (continued). "Notably, fractions of the drug intolerant cells following treatment with apoptosis-inducing concentrations of the drugs were increased in PTX-resistant cancer cells and ABCB1-transfected HEK293 cells, suggesting that P-gp expression is highly correlated, except to CIS cross-resistance." (PMID 27284014, 2016). "Over 80% of all four cells were viable after treated with trametinib at 10 μM, indicating that this dose could be used as the highest concentration to explore the ability of trametinib on enhancing the sensitivity of chemotherapeutic drugs in ABCB1-overexpressing MDR cancer cells." (PMID 25915534, 2015). "Therefore, to look for independent evidence of MEIS1 function within ABCB1 context, we turned to our recently published database of drug sensitivity for a panel of cancer cell lines and the publicly available Broad Institute Cancer Cell Line Encyclopedia (CCLE) microarray database." (PMID 23442791, 2013). "P-gp-ABCB1 reduces intracellular drug concentrations and mitigates their toxicity by facilitating the removal of anticancer drugs, including DOX, from cancer cells." (PMID 40841424, 2025). "This presents a significant clinical challenge in cancer therapeutics, particularly in common malignancies like CRC, where ABCB1 overexpression often correlates with chemotherapy failure." (PMID 40427071, 2025). "In all MDR cancer cell lines tested, incubation of KSQ‐4279 had few effects on ABCB1/ABCG2/ABCC1 expression both in mRNA level and protein level, even given the treated concentration of KSQ‐4279 higher to 50 μM or the incubated time longer to 72 h." (PMID 41328326, 2025). "The ABCB1/ABCG2 efflux system at the BBB poses a significant problem for successful drug delivery to the brain, as it hinders the uptake of anti-cancer drugs into the brain and severely limits their efficacy in treating primary and metastatic brain tumors." (PMID 41574208, 2025). "Our previous works and others elucidated that GCS modulates the β-catenin signaling pathway to up-regulate the expression of ABCB1, FGF2, and METTL3 in cancer cells." (PMID 40507922, 2025). "Well-characterized members of this transporter family include P-glycoprotein (P-gp, also known as MDR-1 or ABCB-1), MRP-1 or ABCC-1, and BCRP or ABCG2, all of which are commonly overexpressed in drug-resistant cancer cells." (PMID 40725123, 2025). "Inhibiting the ABCB1 or ABCG2 transport proteins can abolish chemoresistance and increase the death of chemoresistant cancer stem cells." (PMID 40943558, 2025). "This study revealed that DT improved the efficacy of DOX by strongly suppressing ABCB1 mRNA/protein levels and P-gp activity, thereby outlining a new approach to overcoming MDR in cancer cells." (PMID 40841424, 2025). "COX-2, ABCB1, and ABCG2 overexpression are typically correlated in cancer, contributing to chemotherapy resistance." (PMID 40253988, 2025). "Previous studies showed that aberrantly elevated expression of GCS in turn promotes the overexpression of ABCB1, FGF2, and IL6 in cancer cells." (PMID 40507922, 2025). "This includes the upregulation of main types of ABC transporters (e.g., ABCB1, ABCC1, and ABCG2), which provides the efflux of chemotherapeutic agents from cancer cells." (PMID 41154409, 2025). "Next, EMT is associated with an increased expression of ABC transporters (e.g., ABCB1, ABCG2), which pump chemotherapeutic agents out of the cancer cells." (PMID 41154409, 2025). "In the ABC transporters module, we observed significant upregulation of multidrug efflux pumps that have previously been reported to be upregulated by GH in other cancers: ABCB5 and ABCB1 in both sexes and ABCG2 in males only." (PMID 40806252, 2025). "Three ABC transporters, ABCB1 (P-glycoprotein, P-gp), ABCC1 (multidrug resistance protein 1, MRP1), and ABCG2 (breast cancer resistance protein, BCRP), are key players in multidrug resistance (MDR) phenomena in cancer and microbial infectious diseases." (PMID 40165990, 2025).
cancer (continued). "ABCB1, ABCC1, and ABCG2 transporters are the main contributors to multidrug resistance (MDR) in cancer chemotherapy." (PMID 39200265, 2024). "CD147 is a hub Ag that binds to other proteins (Intergrin, Hyaluronan, CD44, P‐gp/ABCB1, ABCG2, MCT‐1/4, CypA/B, and Gasdermin D) to drive the malignancy of cancer cells." (PMID 38469549, 2024). "High expression of ABCB1 was observed in the ACC cell lines and the six surgical samples, as well as in many of the cancer cells lines of the CCLE." (PMID 39162009, 2024). "ERRγ binds to p65 to upregulate ATP binding cassette subfamily B member 1 (ABCB1) and the rate‐limiting FAO enzyme carnitine palmitoyltransferase 1B (CPT1B), thereby enhancing FAO and drug resistance in cancer cells." (PMID 38721006, 2024). "Some studies have suggested that upregulation of ABC family proteins such as ABCB1, ABCC1 and ABCG2, which transport chemotherapeutic drugs out of cancer cells, is the main reason for chemoresistance in cancer cells." (PMID 38228910, 2024). "The expression of specific target genes, including Bcl-2, MDR1/ABCB1, and MRP1/ABCC1, which regulate apoptosis, autophagy, drug efflux, epithelial to mesenchymal transition (EMT), and cancer stem cells (CSCs), leads to the development of MDR." (PMID 38572428, 2024). "Ovarian and breast cancer overexpress ABCB1 and ABCC10 on their surface to pump paclitaxel out of the cancer cell and develop chemotherapeutic resistance for paclitaxel." (PMID 39003454, 2024). "The binding sites of ABCB1, ABCC1 and ABCG2 are highly flexible and known to bind and transport diverse compounds including anti-cancer drugs." (PMID 38766631, 2024). "ABC transporters such as P-glycoprotein (ABCB1) and breast cancer resistance protein (ABCG2) actively extrude chemotherapeutic agents like Tx from cancer cells, thereby reducing their intracellular concentrations and contributing to resistance." (PMID 38914845, 2024). "Among these subfamilies, ABCB1 is a part of the MDR family and is responsible for facilitating the efflux of chemotherapeutic drugs from cancer cells." (PMID 38674407, 2024). "Hypoxia-induced HIF-1α and HIF-2α have a promoting effect on the expression of ABC transporters, including ABCB1, ABCB5, ABCC1, and ABCG2, and induce drug resistance in cancer cells." (PMID 38725864, 2024). "Doxorubicin is a well-known substrate of both ABCB1 and ABCG2 and an effective chemotherapy drug that has been shown to hinder cancer proliferation of multiple solid tumors." (PMID 38589905, 2024). "ABCB1, ABCC1, and ABCG2, are key members of the ATP-binding cassette (ABC) transporter family, which are crucial for multidrug resistance in cancer cells." (PMID 39574476, 2024). "ABCB1, as an ATP-binding cassette (ABC) transporter, exhibits overexpression in various cancers, leading to resistance against chemotherapeutic drugs with diverse structures." (PMID 39507258, 2024). "The high expression of ABC transporters, particularly ABCB1, ABCC1, and breast cancer resistance protein (BCRP), is a widely recognized molecular mechanism that contributes to MDR in cancer cells." (PMID 39403600, 2024). "The changes in the expressions of the ABCB1, ABCC1, and ABCC2 genes and the levels of the MDR1 and PXR proteins after UA treatment were evaluated in colon LS 174T and prostate DU 145 cancer cells, which differed in the levels of metabolic enzymes." (PMID 39683740, 2024). "The overexpression of P‐gp (ABCB1), ABCC1 and ABCC4 in K562/FLM cells suggests the classic MDR phenotype observed in many resistant cancer cells." (PMID 39046364, 2024).